RNU6-71P (RNA, U6 small nuclear 71, pseudogene)
Synonyms: RNU6-71
Gene: Small nuclear RNA gene on chromosome 13 (36,267,168 to 36,267,274, forward strand). Ensembl gene ENSG00000207203.
Homologues: Orthologues: chimpanzee U6 (99% identical), macaque U6 (98% identical), pig U6 (77% identical). Paralogues in human: RNU6-1024P (93% identical), RNU6-1060P (90% identical), RNU6-266P (90% identical), RNU6-949P (90% identical), RNU6-1013P (89% identical), RNU6-15P (89% identical), RNU6-19P (89% identical), RNU6-474P (89% identical), RNU6-10P (88% identical), RNU6-116P (88% identical), RNU6-12P (88% identical), RNU6-13P (88% identical), and 1286 more.